TG (thyroglobulin)
Diseases named in the same sentence as TG in open-access papers (continued):
Sharing a sentence is not in itself a finding about the gene and the disease.
differentiated thyroid carcinoma (continued). "In our patient, the tumor cells in the pleural effusion showed evidence of adenocarcinoma but were negative for thyroglobulin, suggesting that the cells were from thyroglobulin-immunonegative elements of papillary thyroid carcinoma." (PMID 25532447, 2014). "In conclusion, we report excellent clinical outcomes in properly selected differentiated thyroid cancer patients treated with thyroid lobectomy as primary therapy and followed with serial neck ultrasound and thyroglobulin evaluations." (PMID 24455413, 2013). "The 3-to-12-month monitoring of patients with extrathyroidal invasion or local-regional nodal metastases using ultrasound of neck and serum thyroglobulin should be performed on all patients with differentiated thyroid cancer as per ATA guidelines." (PMID 23326756, 2012). "Previous studies have reported the clinical usefulness of reverse transcription-polymerase chain reaction (RT-PCR) detection of thyroglobulin (TG) mRNA in the peripheral blood of patients with differentiated thyroid carcinoma." (PMID 11437410, 2001). "GM can influence iodine uptake and could be associated to RAI-refractory papillary thyroid carcinoma through different mechanisms involving NIS and thyroglobulin expression as well as TSH levels." (PMID 37824030, 2024). "This measurement serves as a theoretical basis for the monitoring of biochemical recurrence in patients with gastric cancer after total resection, which is similar to the clinical value of serum thyroglobulin in papillary thyroid carcinoma after total thyroidectomy." (PMID 38884851, 2024). "If sufficient fine needle aspiration biopsy material is available, thyroid transcription factor-1, thyroglobulin, or molecular testing may prove useful in differentiating cribriform adenocarcinoma of salivary glands from papillary thyroid carcinoma." (PMID 37069616, 2023). "The blood thyroglobulin level in papillary thyroid carcinoma and blood calcitonin and carcinoembryonic antigen level in medullary carcinoma are useful biomarkers for the evaluation of disease activity, but no effective biomarker has been established for squamous cell carcinoma." (PMID 35022425, 2022). "Intravenous immunoglobulin may be a benign source of transiently high thyroglobulin antibody measured in the follow-up of differentiated thyroid cancer patients." (PMID 36601182, 2022). "Factors influencing serum thyroglobulin levels in patients with differentiated thyroid cancer." (PMID 35721746, 2022). "Similarly, in a review of papillary thyroid carcinoma cohort in our institution, 24% of the patients (20/83) had anti-thyroglobulin antibodies (TG Ab)." (PMID 34512731, 2021). "Serum thyroglobulin is used as part of the early postoperative assessment of differentiated thyroid cancer (DTC) since there is a clear relationship between an increased risk of recurrence and persistent disease after initial treatment and high postoperative stimulated thyroglobulin (ps-Tg) values." (PMID 33053096, 2020). "In patients with papillary thyroid carcinoma who have negative serum thyroglobulin after initial therapy, the risk of structural disease is higher among those with elevated antithyroglobulin antibodies compared to patients without antithyroglobulin antibodies." (PMID 28625809, 2018). "Cytomorphological studies have demonstrated that the tumor cells in the malignant pleural effusion with metastatic well-differentiated papillary thyroid carcinoma are immunoreactive for thyroglobulin, whereas anaplastic carcinoma is known for losing thyroglobulin expression." (PMID 25532447, 2014). "The efficacy of reoperative cervical neck dissection (RND) in achieving biochemical complete remission (BCR) (or postreoperation stimulated thyroglobulin [sTg] of <0.5 ng/mL) remains unclear in persistent/recurrent papillary thyroid carcinoma (PTC)." (PMID 22956067, 2013).
differentiated thyroid carcinoma (continued). "On the other hand, based on expert opinion, British guidelines mentioned that serum thyroglobulin should be checked in all postoperative patients with differentiated thyroid cancer six weeks after surgery and stimulated thyroglobulin indicated 6 months after 131I ablation." (PMID 23326756, 2012). "Predictions of ablation success using post-operative stimulated thyroglobulin or the absorbed dose to the thyroid remnant could inform personalisation of management of differentiated thyroid cancer and identify patients where further treatments or more intensive follow-up are required." (PMID 40532046, 2025). "The assessment of thyroglobulin in fine-needle aspiration washouts is not advised as part of standard diagnostic protocols and is not included in the current Polish guidelines for the evaluation of differentiated thyroid carcinoma in children." (PMID 40003296, 2025). "This case presented the scenario of a patient with tall-cell variant of papillary thyroid carcinoma with two metastatic level VI lymph nodes (1.2 and 0.6 cm) who had undergone therapy with a RAI activity of 100 mCi in the previous year and had a rising serum thyroglobulin of 109 ng/mL." (PMID 39420903, 2024). "In addition, our study investigates the link between survival and prognostic factors such as comorbidities, thyroglobulin levels, treatment activity, tumor multifocality, metastasis presentation and location, residual size, and thyroidectomies subtypes in differentiated thyroid carcinoma patients." (PMID 39583415, 2024). "In papillary thyroid carcinoma (PTC), both thyroglobulin and calcitonin levels increase significantly with the advancing tumor stage, from stage I to stage IV (r = 0.76 and r = 0.65, respectively; p < 0.001)." (PMID 39767732, 2024). "Metastasis was identified in a lymph node at the mediastinum, supporting a diagnosis of usual-type papillary thyroid carcinoma, with positivity for cytokeratin AE1/AE3, thyroglobulin, and TTF-1." (PMID 39553134, 2024). "For instance, in papillary thyroid carcinoma (PTC), thyroglobulin levels increased significantly from 30.5 ng/mL in stage I to 62.0 ng/mL in stage IV (r = 0.76; p < 0.001)." (PMID 39767732, 2024). "We aimed to explore the predictive value of stimulated thyroglobulin (sTg) and pre-ablation antithyroglobulin (pa-TgAb) products for the effect of radioiodine therapy (RAIT) on TgAb-positive differentiated thyroid cancer (DTC) patients." (PMID 37810895, 2023). "Pathology showed papillary thyroid carcinoma with strong and diffuse staining for TTF-1 and thyroglobulin." (PMID 35096430, 2022). "In patients with differentiated thyroid carcinoma (DTC), serum thyroglobulin levels measured at the time of remnant ablation after thyroid hormone withdrawal were shown to have prognostic value for disease-free status." (PMID 34363597, 2021). "The lung nodules were biopsied and revealed papillary thyroid carcinoma with psammomatous calcifications and PAX8, TTF-1, and thyroglobulin immunostaining were reported as positive." (PMID 27774331, 2016). "In papillary thyroid carcinomas the reactivity of TTF-1, thyroglobulin, and CK7 is essentially 100%." (PMID 27774331, 2016). "A 65-year-old man with papillary thyroid carcinoma post two cycles of radioactive iodine therapy on subsequent follow-up showed elevated serum thyroglobulin (>300 ng/mL) and negative iodine scintigraphy (TENIS)." (PMID 42077579, 2025). "An assessment of the thyroglobulin from the fine-needle aspiration washouts was not performed as this is not included in the current Polish guidelines for the evaluation of differentiated thyroid carcinoma in children." (PMID 40003296, 2025). "This was a 73-year-old male who underwent total thyroidectomy for bilateral papillary thyroid carcinoma (no lymph nodes involvement) at the level of the orthotopic gland with post-operatory high serum thyroglobulin that required additional imaging exploration." (PMID 38791947, 2024).
differentiated thyroid carcinoma (continued). "Patients with papillary thyroid carcinoma (PTC) and the BRAF mutation showed higher mean thyroglobulin levels (45.2 ± 22.5 ng/mL) compared to those without the mutation (28.5 ± 14.0 ng/mL), suggesting more intense tumor activity or a larger tumor mass." (PMID 39767732, 2024). "Metastasis was identified in a lymph node, supporting the diagnosis of usual-type metastatic papillary thyroid carcinoma, with positivity for cytokeratin AE1/AE3, thyroglobulin, and thyroid transcription factor 1 (TTF-1), confirming usual-type metastatic papillary carcinoma." (PMID 39553134, 2024). "We found that in patients with medullary thyroid carcinoma (MTC) and papillary thyroid carcinoma (PTC) serum calcitonin and thyroglobulin levels changed exponentially over time, respectively, and that doubling times of these values were very strong prognostic factors." (PMID 36153411, 2023). "It was negative for thyroglobulin and thyroid transcription factor-1, which was in keeping with cribriform adenocarcinoma of salivary glands rather than papillary thyroid carcinoma." (PMID 37069616, 2023). "In one research, it was found that the mean SUVmax of the suspected lesions after performing PET/CT in patients with differentiated thyroid cancer with elevated thyroglobulin levels and negative 131I whole-body scan findings was 2.9 ± 4.5 points." (PMID 35904608, 2022). "The aim of this study was to assess the clinical impact of 18F-FDG PET/CT on the management of patients with differentiated thyroid carcinoma who had elevated serum thyroglobulin (Tg) and negative 131I whole body scan (WBS)." (PMID 35083346, 2022). "The expression of serum triiodothyronine, tetraiodothyronine, thyrotropin, thyroglobulin antibody and thyroid peroxidase antibody and NDRG3 were significantly different among benign thyroid nodules, papillary thyroid carcinoma cases and healthy control groups (P <0.001)." (PMID 36619553, 2022). "The aim of this study was to assess the diagnostic efficiency of TSH-stimulated 18F-FDG PET/CT in radioiodine-negative differentiated thyroid carcinomas (DTCs) with different levels of TSH stimulated thyroglobulin (TSH-Tg)." (PMID 27090254, 2016). "Given that the bulk of the patient's tumor was primarily a well-differentiated papillary thyroid carcinoma and the anaplastic component was focal as well as multifocal, it is not surprising that the patient had elevated thyroglobulin levels." (PMID 27774331, 2016). "Ma C, Xie J, Lou Y, Gao Y, Zuo S & Wang X. The role of TSH for 18F-FDG-PET in the diagnosis of recurrence and metastases of differentiated thyroid carcinoma with elevated thyroglobulin and negative scan: a meta-analysis." (PMID 27090254, 2016). "• Serum thyroglobulin (Tg) should be checked in all post-operative patients with differentiated thyroid cancer (DTC), but not sooner than six weeks after surgery." (PMID 27841128, 2016). "The diagnosis of papillary thyroid carcinoma can become challenging, that is, in its differentiation from a primary lung carcinoma, when the thyroglobulin immunohistochemical stain is negative." (PMID 27774331, 2016). "Stimulated thyroglobulin (sTg) is not recommended for the follow-up of patients with papillary thyroid carcinoma (PTC) submitted only to thyroidectomy (without radioiodine)." (PMID 26346672, 2015). "Thyroglobulin was positive in metastatic papillary thyroid carcinoma, but negative in primary lung adenocarcinoma." (PMID 23414265, 2013). "A negative expression of thyroglobulin excludes the diagnosis of papillary carcinoma of the thyroid, which stains positive to both markers." (PMID 21167048, 2010). "Supposedly, thyrocyte-specific transcripts such as thyroglobulin (Tg) and thyroid-stimulating hormone receptor (TSH-R) were proposed to be useful for the diagnosis of circulating tumour cells in patients suffering from differentiated thyroid carcinoma (DTC)." (PMID 16091757, 2005).
differentiated thyroid carcinoma (continued). "The prognostic value of thyroglobulin antibody (TgAb) and its trends during follow-up periods may guide the treatment plans in patients with differentiated thyroid cancer (DTC) following surgery, however, there is still a lack of sufficient data." (PMID 39968066, 2025). "18F-FDG PET/CT is able to improve diagnostic accuracy and have management impact in a therapeutically relevant way in patients with differentiated thyroid carcinoma who present with rising thyroglobulin level, negative 131I WBS, and clinical suspicion of recurrent disease." (PMID 35083346, 2022). "Differentiated thyroid cancer (DTC) patients with negative serum thyroglobulin (Tg), negative 131I whole–body scintigraphy (131I-WBS) at first post-ablation and progressively increased TgAb level are a relatively rare entity in the follow-up after total thyroidectomy and radioactive iodine therapy." (PMID 28588229, 2017). "In clinical practice, approximately 10-25% of post-surgical differentiated thyroid carcinoma (DTC) patients with high serum thyroglobulin (Tg) and negative 131I whole-body scan (WBS) have poor prognosis due to recurrent or metastatic lesions after radioactive iodine treatment." (PMID 27904869, 2016). "Although serum thyroglobulin is a useful marker after total thyroidectomy for papillary thyroid carcinoma (PTC), it is not a reliable marker for patients with a high titer of anti-thyroglobulin antibodies or when transformation to undifferentiated carcinoma has occurred." (PMID 24407283, 2014). "Although serum thyroglobulin is a useful marker in patients who have undergone total thyroidectomy for papillary thyroid carcinoma (PTC), it is not a reliable marker in those with a high titer of anti-thyroglobulin antibodies or when transformation to undifferentiated carcinoma has occurred." (PMID 24407283, 2014). "Adjuvant 131I treatment increases specificity of the further serum thyroglobulin follow-up, as in patients operated because of differentiated thyroid carcinoma but not treated by 131I the source of Tg might be both healthy thyroid cells and cancer cells." (PMID 21040579, 2010). "On the contrary, the papillary thyroid carcinoma stained positive for CK, CK19, and thyroglobulin, and negative for vimentin." (PMID 41124647, 2026). "We excluded the possibility of these malignant tumors according to immunohistochemical markers such as thyroglobulin, CK19, MC, and CyclinD1, all of which were found to be negative, ruling out papillary carcinoma of the thyroid." (PMID 32430041, 2020). "However, in immunohistochemistry studies, TCCRP exhibits no concordance with thyroid-specific markers Thyroid Transcription Factor-1(TTF-1), Thyroglobulin(TG), which proves that TCCRP lesions do not occur as a result of breast metastasis of papillary thyroid carcinoma." (PMID 41256322, 2025). "In cases with differentiated thyroid cancer, further total thyroidectomy (if was not already provided) is mandatory followed by the application of radioiodine ablative therapy, TSH-suppressive therapy with daily oral thyroxine, and the use of thyroglobulin lifelong periodical check-up." (PMID 38791947, 2024).
papillary thyroid carcinoma (103 papers, 2008 to 2026). "Another important molecular alteration in PTC is the loss of Thyroid Differentiation Markers: As papillary thyroid cancer progresses, there is often a loss of expression of thyroid‐specific genes like thyroglobulin and sodium‐iodide symporter (NIS)." (PMID 40344620, 2025). "Elevated concentrations of thyroglobulin eluent is a risk factor for lateral cervical lymph node metastasis (LLNM) in patients with papillary thyroid cancer (PTC)." (PMID 38089614, 2023). "Despite the anti-TB treatment, the persistence of high levels of thyroglobulin and the presence of a hard thyroid nodule led to subtotal thyroidectomy with unilateral neck dissection revealing a papillary carcinoma associated with a tuberculosis of the gland." (PMID 25745526, 2014). "Papillary thyroid carcinoma is an uncommon cause of malignant pleural effusion, with only 10 cases in total reported in the literature, their physical characteristics rarely documented and their composition (for example thyroglobulin levels) seldom described." (PMID 23724969, 2013). "It holds significant value in the postoperative period, and somehow, the goal of surgery in papillary thyroid cancer (PTC) undergoing total thyroidectomy is to achieve undetectable levels of postoperative thyroglobulin (uTg)." (PMID 39766029, 2024). "The value of lymph node ratio and preoperative thyroglobulin levels in predicting disease free survival in papillary thyroid cancer." (PMID 36560883, 2023). "A 70-years-old woman with a previous history of papillary thyroid cancer and loco-regional lymph nodes metastases came at our observation for a sudden rise of anti-thyroglobulin antibody (anti-Tg Ab) levels 14 years after initial treatment." (PMID 33599943, 2021). "The anti-thyroglobulin antibody (TgAb) has been suggested to be more common in patients with papillary thyroid cancer (PTC)." (PMID 32760349, 2020). "HE staining of bone metastases revealed nuclear features of papillary carcinoma, and immunostaining was positive for thyroglobulin and PAX-8." (PMID 32328315, 2020). "The histologic examination revealed a well differentiated papillary carcinoma, classical variant, with multiple microscopic foci in both lobes of the thyroid gland; the tumor stained positively for TTF1 and Thyroglobulin." (PMID 28810922, 2017). "Thyroglobulin (Tg) is another important biomarker for monitoring the progression of thyroid cancer especially papillary thyroid cancer." (PMID 28378396, 2017). "Thyroglobulin measurement in fine-needle aspiration washout fluid (FNA-Tg) is widely used for detection of lymph node metastasis (LNM) in patients with papillary thyroid cancer (PTC)." (PMID 26121598, 2015). "Negativity for TTF-1 and thyroglobulin expression, which are markers for follicular and papillary carcinomas, as well as for calcitonin, a marker of medullary thyroid carcinoma, excluded the possibility of these tumors, more commonly found in the thyroid." (PMID 25295208, 2014). "The thyroid-targeted expression of the human RET/PTC3 oncogene under the control of the bovine thyroglobulin promoter in transgenic mice, induces metastatic solid-type papillary carcinomas considered as analogous to the human solid-type PTC." (PMID 18985036, 2008). "Therefore, from a biochemical standpoint, the goal of surgery in papillary thyroid cancer is to achieve undetectable levels of postoperative thyroglobulin." (PMID 39766029, 2024). "Mounting evidence shows that low- and intermediate-risk papillary carcinoma submitted to thyroidectomy without neck dissection can be safely monitored with thyroglobulin." (PMID 35758832, 2022). "We present the case of a 71-year-old Caucasian man with metastatic papillary thyroid cancer; a large, long-standing, right-sided pleural effusion and a 83-fold higher pleural thyroglobulin level compared to corresponding serum, supporting this malignancy as the cause of the patient’s effusion." (PMID 23724969, 2013).